TNF (tumor necrosis factor)
Diseases named in the same sentence as TNF in open-access papers (continued):
Sharing a sentence is not in itself a finding about the gene and the disease.
osteoarthritis (continued). "Tumor necrosis factor (TNF) may play an important role in the inflammatory responses that occur during osteoarthritis, triggering the production of IL-6, IL-8, and RANTES by human articular chondrocytes." (PMID 36362117, 2022). "Furthermore, inhibition of TNF-α and IL-8 gene expression in osteoarthritis is mediated in part by GlcN-induced O-GlcNAcylation." (PMID 35203353, 2022). "Studies have shown that Mg2+ may affect osteoarthritis by inhibiting the expression of IL-1β, TNF-α, MMP13, and ADAMTS5 genes in macrophages, synoviocytes, and chondrocytes." (PMID 36546928, 2022). "The pathogenesis of RA involves many immune cells and cytokines, including interleukin-1 (IL-1), interleukin-6 (IL-6), interleukin-18 (IL-18), and tumor necrosis factor (TNF) as the main pro-inflammatory cytokines, which induce inflammatory response and osteoarthritis injury." (PMID 35833125, 2022). "In addition, allicin ameliorates the progression of osteoarthritis by decreasing TNF-α, IL-6, and IL-1β in chondrocytes." (PMID 34445305, 2021). "Besides, miR-23b restoration promoted the release of proinflammatory factors, including IL-6, IL-8 and TNF-α, and accelerated the apoptosis rate of knee joint chondrocytes, thus promoting the development of degenerative joint disease." (PMID 34046827, 2021). "Taken together, the results of this study suggest that modulating expression of IL-33, IL-6, TNF-α, TLRs, DAMPs, and MMPs with vitamin D supplementation may serve as a novel therapeutic to attenuate inflammation and cartilage degeneration in osteoarthritis." (PMID 34842603, 2021). "Previous studies have shown that inhibiting TNF-α in RA reduces local osteoarthritis through a reduction in synovial cell infiltration and the expression of adhesion molecules, chemokines, and cytokines, coinciding with reduced levels of acute phase reactants such as CRP and interleukin (IL)-6." (PMID 34209821, 2021). "The PI3K/AKT signaling pathway is an inflammatory pathway that may be mediated by TNF-α in osteoarthritis, and TNF-α inhibitor treatment significantly reduced the expression of IL-1, IL17a, and IL8 in synovial fibroblasts." (PMID 35046814, 2021). "Furthermore, moracin, a flavonoid from Mores alba root bark protects against IL-1β-induced osteoarthritis by reducing inflammatory factors (TNF-α, IL-6, and COX2) via attenuating the NF-κB pathway." (PMID 33371279, 2020). "Here, we report the effects of the novel agent APPA, undergoing formal clinical development for treatment of osteoarthritis, and its constituent components, apocynin (AP) and paeonol (PA) on a number of neutrophil functions, including effects on TNFα- expression and signalling." (PMID 32383062, 2020). "However, expression of these cytokines in osteoarthritis pain remains unresolved, and different studies have arrived at conflicting conclusions regarding interleukin 1β (IL-1β), interleukin 6 (IL-6) and tumor necrosis factor (TNF-α)." (PMID 32059658, 2020). "Pro-inflammatory cytokines including IL-1β and TNF-α play an important role in osteoarthritis." (PMID 33233504, 2020). "In addition, there is evidence in experimental animals that sclerostin generated in response to TNF-α and IL-1β improves post-traumatic osteoarthritis by inhibiting the activity of proteolytic enzymes involved in cartilage degradation." (PMID 32947946, 2020). "Results demonstrated that “Apoptosis”, “TNF signaling pathway”, “PI3K-Akt signaling pathway”, “MAPK signaling pathway” and “IL-17 signaling pathway” were highly associated with the onset and progression of osteoarthritis." (PMID 32874205, 2020). "PI3K/Akt pathway was associated with TNF-α-induced activation of OA FLS, which may involve in the pathogenesis of osteoarthritis." (PMID 31829201, 2019). "Moreover, altered expression of miR-9 was found during screening osteoarthritis cartilage involved in the control of tumor necrosis factor α (TNFα) expression." (PMID 30717449, 2019).
osteoarthritis (continued). "In an important study, the cytokine profile in patients with symptomatic cartilage defects as well as osteoarthritis (OA) revealed elevated levels of catabolic cytokines, including interleukin (IL), − 6 and tumor necrosis factor (TNF) α, in the synovial fluid and cartilage tissue extracts." (PMID 31054572, 2019). "The purpose of this study was to investigate the influence of moderate physical activity (MPA) on the expression of osteoarthritis (OA)-related (IL-1β, IL-6, TNF-α, MMP-13) and anti-inflammatory and chondroprotective (IL-4, IL-10, lubricin) biomarkers in the synovium of an OA-induced rat model." (PMID 30691048, 2019). "This reduction in TNF-α concentration for males may have the potential to improve post-injury outcomes, since the cytokine was recently identified as a marker for early osteoarthritis, a common long-term consequence of ACL injury." (PMID 30596697, 2018). "Interestingly, a decreased expression of miR-130a has been shown to correlate with TNF-α in the development of osteoarthritis." (PMID 29850558, 2018). "This study aimed at assessing the effectiveness and safety of repeated administrations of allogeneic bone marrow-derived mesenchymal stem cells (BM-MSCs) primed with tumor necrosis factor (TNF)-α and interferon-γ in an equine model of chemically-induced osteoarthritis." (PMID 30119668, 2018). "TNF-α, produced by monocytes, macrophages, and lymphocytes, is a well-studied master pleiotropic inflammatory cytokines, attributing to the induction of many pathogenesis or diseases including osteoclastogenesis and osteoarthritis." (PMID 30061878, 2018). "It’s reported Atsttrin was therapeutic in inflammatory arthritis mice model; moreover, overexpression of Atsttrin in local articular cartilage protected against osteoarthritis; and study showed that Atsttrin promoted bone healing through inhibiting TNF-α pathway in the physiological process." (PMID 29312639, 2017). "In addition to chondrocytes, macrophages contribute to inflammation and matrix degradation in osteoarthritis tissues, and inflammatory mediators such as IL-1β, TNF-α, IL-6, PGE2, and NO represent potential targets for osteoarthritis disease modification." (PMID 27411719, 2016). "In addition, Litsea japônica fruits have been studied, showing that their extract can perform several activities, such as anti-osteoarthritis and activation of tumor necrosis factor-α (TNF-α)." (PMID 28119671, 2016). "It is thought that IL1-β and TNF-α play an important role in the development of osteoarthritis." (PMID 25822615, 2015). "Moreover, ADAMTS-7 and tumor necrosis factor-α (TNF-α) form a positive feedback loop in osteoarthritis." (PMID 26696755, 2015). "It has been suggested that, in the osteoarthritis synovium, both inflammatory and destructive responses are dependent largely on macrophages and that these effects are cytokine-driven through a combination of IL-1 and TNF-α." (PMID 23597113, 2013). "Furthermore, the influence of IL-1β and TNF-α as the major pro-inflammatory cytokines released within the joint after trauma and involved in the initiation and progression of degenerative joint disease was investigated." (PMID 24034344, 2013). "In fact, recently reported ginsenosides showed anti-osteoarthritis activities through regulation of inflammation which drives the production of enzymes such as MMPs to break down the extracellular matrix of cartilage via regulation of pro-inflammatory cytokines such as IL-1β and TNF-α." (PMID 40507179, 2025). "Osteoarthritis (OA) is a degenerative musculoskeletal disorder marked by progressive cartilage degradation, synovial inflammation and subchondral bone remodeling, driven by pro-inflammatory mediators such as interleukin-6 (IL-6) and tumor necrosis factor-alpha (TNF-α)." (PMID 41623825, 2025).
osteoarthritis (continued). "This suggests that GLP-1RAs may modify the inflammatory cascade of osteoarthritis (OA) by modifying the secretion of cytokines and tumor necrosis factor-α (TNF-α), the pro-inflammatory molecules that are produced by macrophages responsible cartilage degradation and synovial inflammation." (PMID 40372699, 2025). "Moreover, the inhibition of the NF-κB signaling pathway by IL-1β and TNF-α decreases the inflammation of joints and tissue degradation and prevents the effects of iNOS and MMP, which cause inflammation and articular cartilage breakdown in osteoarthritis." (PMID 39204123, 2024). "Mechanistically, these anti-osteoarthritis effects were associated with upregulated expression of COL2A1 and aggrecan in the articular cartilage, along with a decrease in inflammatory mediators (NO, PGE2), cytokines (IL-6, IL-1, TNFα), and cartilage-degrading enzymes (MMP-3 and MMP-13) in serum." (PMID 39519204, 2024). "Pro-inflammatory cytokines such as TNFα, IL-1β, and IL-6 accelerate the aging process of mesenchymal stem cells, impairing their ability to differentiate into other cells and subsequently alter osteochondral homeostasis in the elderly population, leading to osteoarthritis." (PMID 38201942, 2023). "Patients with degenerative joint disease, when exposed to leptin, respond by producing proinflammatory cytokines such as IL-8, IL-6, and TNF-alpha, which may intensify the catabolism of proteoglycans, increase the expression of metalloproteinases (MMP), and thereby stimulate cartilage degradation." (PMID 38203376, 2023). "Moreover, previously, we reported that morroniside can improve the progression of osteoarthritis by inhibiting canonical NF-κB p65/RelA signaling, suggesting morroniside could ameliorate TNFα-induced muscle atrophy." (PMID 36618945, 2022). "In addition, the factors used to treat osteoarthritis include TNF-α, IL-6, MMP3 and MMP13." (PMID 35566359, 2022). "The RT-PCR data manifested that the expression of M1 macrophage markers (TNF-α, IL-1β, and iNOS) were significantly upregulated, while the expression of M2 macrophage markers (IL-10 and Arg-1) was significantly downregulated in synovial tissues of osteoarthritis patients." (PMID 34652255, 2021). "Functional analysis of lncRNA in the synovial membrane of osteoarthritis patients revealed that lipopolysaccharide, angiogenesis, tumor necrosis factor (TNF) signaling, and mitogen-activated protein kinase (MAPK) signaling pathways might contribute to OA development." (PMID 33579305, 2021). "In the osteoarthritic milieu, mechanical stress or pro-inflammatory cytokines, like TNF and IL1B, leads to NF-κB-pathway activation, which causes the expression of catabolic factors like NO, MMPs and ADAMTS proteases inducing cartilage breakdown and progression of osteoarthritis." (PMID 34440921, 2021). "Inflammatory cytokines, including IL-1β, TNFα, and IL-6, play a key role in osteoarthritis, and IL-6 is considered to be the key cytokine; its effect is mainly based on promoting the formation of osteoclasts and bone resorption while synergism with IL-1β and TNFα." (PMID 31139654, 2019). "Furthermore, the use of IL-1 and/or TNF-α inhibitors in experimental models of inflammatory arthritis and OA has provided strong support for the role of IL-1 in the regulation of catabolic events and inflammatory processes in degenerative joint diseases." (PMID 30340603, 2018). "As expected, our findings suggest that the anti-inflammatory effects of Guilu Erxian Liquid (GE-L), following marked decrease on both IL-1β and TNF-α during the early course of post-traumatic osteoarthrosis (OA), may be of potential value in the treatment of osteoarthritis." (PMID 30340603, 2018). "This link between PRR5L, TTP, and TNFα is interesting in light of recent studies demonstrating the association of a SNP (rs4755450) in PRR5L with juvenile idiopathic arthritis, and a microarray study showing that down-regulation of PRR5L was associated with osteoarthritis in adults." (PMID 27539829, 2017).
osteoarthritis (continued). "Furthermore, the expression of BMP-6 and BMP-7 was also decreased in articular cartilage of TNF-transgenic mice, suggesting that loss of BMP expression could be also involved in chronic inflammatory and not only degenerative joint diseases." (PMID 16542506, 2006). "Indeed, this Uncaria guianensis extract is a remarkably potent inhibitor of NF-κB activity and tumor necrosis factor (TNFα) production, with clear cytoprotective actions and has already successfully completed a placebo controlled trial for osteoarthritis of the knee." (PMID 16242032, 2005). "In accordance with the proposed role of NOTCH2 in inflammation, Notch2tm1.1Ecan mice are sensitized to the osteoarthritis that follows DMM surgeries and to the osteolytic actions of tumor necrosis factor α (TNFα)." (PMID 40345585, 2025). "Collectively, these findings suggest that inducible activation of TIPE2 can reduce or inhibit TNF-α secretion, suppress SASP and inflammation, and ultimately alleviate cellular senescence and osteoarthritis." (PMID 40759632, 2025). "This includes lutikizumab (anti-IL1a and IL1b) for osteoarthritis, and COVA322, a bispecific TNF/IL17A antibody fusion protein studied in phase 1/2 in patients with stable chronic moderate-to-severe plaque Pso (stopped for safety reasons)." (PMID 40529150, 2025). "Increased levels of IL-1β, IL-6, TNF-α, and PGE2 were reported in synovial fluid samples from patients with TMD, particularly in cases with degenerative joint disease and internal derangement." (PMID 40649748, 2025). "In osteoarthritis, GBP5 expression is significantly upregulated in TNF‐α‐treated chondrocytes, where IRF1 promotes GBP5 transcription, triggering NLRP3 inflammasome activation and promoting pyroptosis." (PMID 40636987, 2025). "Fibroblast-like synoviocytes (FLS) from patients with osteoarthritis (OA) and RA and 3D synovium micromasses, formed by RA FLS and RA monocytes, were stimulated with Sema4B and TNF-α alone and in combination." (PMID 40598553, 2025). "In a mouse model of posttraumatic osteoarthritis, curcumin has been found to slow the progression of osteoarthritis and relieve its symptoms by reducing the levels of MMP-1, MMP-3, MMP-13, ADAMTS5, IL-1β, and TNF-α." (PMID 37938371, 2024). "Articular chondrocytes from MT-COMP/CHOP−/− mice displayed higher IL-10 and lower TNFα levels, which influenced key molecules such as SIRT1 and MMP-13, both critical to joint health and osteoarthritis progression." (PMID 39795874, 2024). "Based on 15 studies, they conclude that resveratrol suppresses joint inflammation, marked by reduced pro-inflammatory markers (IL-1, TNFα, IL6, NO), reduces chondrocyte apoptosis and improves cartilage structure in animal models of osteoarthritis." (PMID 39519204, 2024). "The main inflammatory factors regulated by circRNAs were IL-6/IL-8/TNF-α/IL-17, and IL-1β and TNF-α also induced most osteoarthritis in vitro cell models." (PMID 37229197, 2023). "Specifically, inflammatory cartilage tissue releases cytokines such as interleukin (IL)-1β, IL-6, and tumor necrosis factor-α (TNF-α), which are responsible for cartilage matrix degradation and bone destruction in osteoarthritis." (PMID 37718444, 2023). "For further investigation of the potential role played by TRB3 in chondrocytes in osteoarthritis patients, the TRB3 level was subsequently examined in a TNF-α-induced osteoarthritis model in vitro." (PMID 35776529, 2022). "SA alleviated the progression of osteoarthritis (OA) by reducing the levels of IL-1β, IL-6, prostaglandin E2 (PGE2), nitric oxide (NO), and TNF-α in vitro." (PMID 35204088, 2022). "We next examined the levels of TNF-α, IL-6, IL-10 and vascular endothelial growth factor (VEGF) in the serum samples of experimental animals after induction of osteoarthritis." (PMID 35887046, 2022).
osteoarthritis (continued). "NF-κB suppression repressed the downstream inflammatory mediators as proved in an in-vitro experiment on osteoarthritis, which reported the TCA-induced decline in TNF-α and COX-2 levels." (PMID 35648328, 2022). "Studies showed that glycyrrhizin treatment suppressed IL-1β-induced NF-κB phosphorylation in a mouse model of osteoarthritis (OA), significantly reducing IL-6, prostaglandin E2 (PGE2), nitric oxide (NO) and TNF-α levels." (PMID 35684415, 2022). "Among them, Ribosomal proteins were upregulated in the synovial membranes of female patients with Osteoarthritis, Carhsp1 can regulate the stability of TNF -α mRNA, they might be associated with RA, no other proteins, such as Wars, Yars, Bzw2, Mcts1 and Eif4b were reported in RA." (PMID 35006449, 2021). "During the occurrence of osteoarthritis, CXCL8 (C-X-C Motif Chemokine Ligand 8) and TNF-α (Tumor necrosis factor α) can induce the expression of S100A11 and promote its release to the extracellular space to form a dimer." (PMID 34179021, 2021). "TNF-α, an important proinflammatory cytokine, has been reported to be elevated in sera and synovial membranes of AOSD patients compared with osteoarthritis patients or healthy subjects." (PMID 34239943, 2021). "In a cell study with human chondrocytes (cells that make up cartilage), the anti-inflammatory action of IL-10 protects against damage from tumor necrosis factor-alpha (TNF-α), a pro-inflammatory mediator elevated in osteoarthritis." (PMID 32316397, 2020). "As reported in this recent work, the pre-treatment with RPH had a suppressive effect on the mediators that contributed to the progression of osteoarthritis by inhibiting collagen 2, COX-1-2, MMP-13, TNF-α, and IL-13 expression." (PMID 32340224, 2020). "Our results reveal that DHC possesses a beneficial effect against TNF-α-mediated insult in human chondrocytes, implying a potential role for DHC in the treatment of osteoarthritis (OA)." (PMID 32924970, 2020). "On the other hand, in a mouse model with osteoarthritis, the animals’ treatment with grapes procyanidins was shown to downregulate VEGF, TNFα, Il6 and RANKL expression, protecting the cartilage integrity." (PMID 32664580, 2020). "In addition to detecting the IL-1β, TNF-α, IL-6, IL-17, IL-8, IL-4, IL-10, and IL-13 cytokines, the kit can also detect additional 28 cytokines, so we can also explore whether other factors are involved in the pathogenesis of osteoarthritis." (PMID 32332638, 2020). "Increased protein levels of TNF-α, TNF-R1, and TNF-R2 were retained in vitro by HA fibroblast-like synoviocytes (n = 6) with respect to osteoarthritis control fibroblast-like synoviocytes (n = 6)." (PMID 31261789, 2019). "Taken together, hyperacute serum can be a promising blood separation product in degenerative joint diseases, which enhances cell proliferation, the production of COL1A1 and osteonectin, while decreasing the level of RANKL, IL-1β, IL-6Rα, IL-12, and TNF-α." (PMID 31382623, 2019). "All these results indicate that OA inducers, including IL-1β, TNF-α, and H2O2 can promote progression of osteoarthritis in different ways." (PMID 31772142, 2019). "In vitro and in vivo studies demonstrated that CJM reduced the IL‐1β‐, IL‐6, IL‐17‐ and TNF‐α‐induced up‐regulation of MMP3, MMP13, ADAMTS4, ADAMTS5 and COX‐2 and blocked osteoarthritis development in a destabilization of the medial meniscus mouse model." (PMID 31148341, 2019). "In addition, the levels of COMP and TNF-α varied significantly among groups A, B, and C (p < 0.01 or P < 0.05), which suggested that the injection with increasing amounts of MIA caused knee osteoarthritis of increasing severity (light, mild, and heavy osteoarthritis)." (PMID 30105061, 2018). "In the study of osteoarthritis, the production of OPG can be promoted by dandelion's ability to inhibit the concentration of RANKL and increase the production of TNF-α and IL-10 in serum, manifesting as an anti-inflammatory effect." (PMID 28572831, 2017).